CRP (C-reactive protein)
Diseases named in the same sentence as CRP in open-access papers (continued):
Sharing a sentence is not in itself a finding about the gene and the disease.
depression (continued). "For subjects with average post-treatment CRP levels, every 10% increase in CRP at T2 was associated with a .001% decrease in severity of neurovegetative symptoms of depression (b = −.0001, t = -3.292, p = .004)." (PMID 39834556, 2025). "The associations observed with CRP, alcohol use disorder, depression, and insomnia symptoms support potential common genetic factors underpinning these traits and neuropathic pain." (PMID 39471050, 2025). "In these replications, we confirmed that IL6 perturbation is associated with lower odds of depression (OR per 24% CRP decrease of 0.993, 95% CI 0.989 to 0.997, P = 0.002) and cholelithiasis or cholecystitis (OR of 0.896, 95% CI 0.803 to 0.999, P = 0.048)." (PMID 40858837, 2025). "Future studies should combine biomarkers (e.g. IL-6, CRP) and psychosocial variables to uncover the multilevel mechanisms underlying the somatization-depression relationship." (PMID 40236492, 2025). "A recent review also suggests that CRP and IL‐6 mediate the association between adverse childhood experiences and adult depression." (PMID 41014304, 2025). "Specifically, lower difficulties in positive emotion regulation were associated with higher CRP and IL-6 levels correlated with decreased depression scores and reduced stress responses, respectively." (PMID 41333345, 2025). "The level of CRP was associated with depression and sleep disturbances, although its relationship with anxiety remained unclear." (PMID 40927014, 2025). "In depression, the Maastricht study has found that elevated serum biomarkers of inflammation such as the acute phase reactant C-reactive protein (CRP) and TNF-a were associated in both major and minor depressive episodes." (PMID 40529210, 2025). "This includes prospective and genetic evidence linking elevated inflammatory signaling to depression risk (e.g., childhood IL-6/CRP predicting adult depression; IL-6 pathway Mendelian randomization), and associations with aggression-related psychopathology." (PMID 41008344, 2025). "While there is convincing research linking depression and inflammation, a definitive causal relation with specific biomarkers, such as CRP, has yet to be conclusively identified." (PMID 41661985, 2025). "Two meta-analyses have reported direct associations between depression and inflammation, as measured by CRP, in both adolescents and adults." (PMID 40565981, 2025). "Major depressive disorder is associated with pro‐inflammatory markers, including C‐reactive protein (CRP), cytokines, neopterin, and tryptophan catabolites, which serve as diagnostic and treatment biomarkers in humans." (PMID 41404534, 2025). "Higher CRP levels frequently precede the onset of depression in population studies, and Mendelian randomization suggests causal links between IL-6, CRP, and depression." (PMID 41333345, 2025). "Although CRP and IL-6 are well-established inflammatory markers that have been linked to depression in multiple studies, their specificity for depression is constrained by associations with various physical conditions." (PMID 40276074, 2025). "Through formal mediation analyses, we quantified the reciprocal pathways between depression and CRP in CVD risk." (PMID 40904459, 2025). "Weighted logistic regression analyses of association between the C-reactive protein to lymphocyte ratio and depression." (PMID 40535425, 2025). "CRP is a well-established low-grade, peripheral, systemic proinflammatory activity marker and has been linked to depression, rendering it a critical biomarker to explore as a distal risk factor of high MDD severity." (PMID 40686933, 2025). "Chronic inflammation has been linked to depressive disorders, with elevated levels of inflammatory markers such as C-reactive protein (CRP), IL-1β, and TNF-α correlating with symptom severity." (PMID 40896230, 2025).
depression (continued). "In bivariate correlation analysis, fatigue was strongly associated with pain (r = 0.50), depression (r = 0.44), and anxiety (r = 0.33), moderately associated with Hb levels (r = −0.21), and weakly associated with CRP levels (r = 0.18)." (PMID 38819432, 2024). "In this study, two proteins (CSPG3 and GCKR) were linked with eight NAFLD risk factors (BMI, waist circumference, smoking initiation, major depression, iron levels, C-reactive protein levels, galectin-3, and HDL cholesterol)." (PMID 38782984, 2024). "A proposed mechanism for elucidating how poor sleep quality increases depression risk is an increase in the expression of inflammatory markers, such as C-reactive protein and interleukin-6 (IL-6)." (PMID 39850107, 2024). "Higher pre-pandemic PA was associated with reduced odds of depression (OR = 0.964, 95%CI [0.948, 0.981]) and anxiety (OR = 0.976, 95%CI [0.953, 1.000]), whereas elevated CRP was associated with 1.343 times higher odds of depression (95%CI [1.100, 1.641])." (PMID 38699297, 2024). "Previous studies have found that associations of C-reactive protein, lymphocyte to monocyte ratio and neutrophil to lymphocyte ratio with the risks of any psychiatric disorder, depression, anxiety, and stress-related disorders." (PMID 39687490, 2024). "First, we used cross-sectional and longitudinal non-genetic analysis examine the association between circulating levels of CRP and depression/cognitive performance." (PMID 38699368, 2024). "Secondary outcomes include assessing the impact of these supplementations on additional markers such as plasma levels of inflammation markers CRP and IL-6, cardiovascular risk factors, and depression." (PMID 39139799, 2024). "Elevated CRP levels have also been observed in patients with depression, which is another a high risk factor for coronary heart disease in women." (PMID 39759498, 2024). "The effect estimates for the associations of the novel measure with depression outcomes were comparable to those for individual immune proteins (i.e., IL-6, CRP, sIL-6R)." (PMID 38442505, 2024). "One study reported that elevated CRP levels were associated with an increased risk of depressive relapse, and a strong association between inflammatory processes and recurrent major depressive disorders has been suggested." (PMID 38414502, 2024). "Based on multiple regression, while controlling for disability (mRS) and history of depression, CRP remained associated with average FSS score (β = 0.49, p = 0.03)." (PMID 38533609, 2024). "Elevated CRP levels are associated with depression, with capacity to indicate the presence of chronic inflammation." (PMID 38956594, 2024). "For example, in a study with 667 outpatients with CHD, greater depressive symptoms were associated with higher subsequent levels of IL-6 and CRP, and persistent depression had a greater effect on inflammation than a single episode of depression." (PMID 38820248, 2024). "Specifically, neutrophils, leukocytes, and serum CRP showed comparably large effect sizes, where one SD increase corresponds to about 10% higher risk of developing depression." (PMID 38782943, 2024). "previously investigated the relationship between hs-CRP levels in Korean adults and the risk of depression." (PMID 38596631, 2024). "Older adults with elevated levels of CRP (LGI) before the pandemic had 1.34 times higher adjusted risk of developing clinically significant symptoms of depression and anxiety." (PMID 38699297, 2024). "Inflammation is a critical element in the pathogenesis of psychological disorders, with elevated C-reactive protein levels associated with anxiety and depression." (PMID 38500549, 2024). "Numerous population-based studies have found prospective associations between depression and biomarkers of systemic inflammation such as C-reactive protein." (PMID 38497671, 2024). "A recent study found a strong association between CRP and depression in women that aligns with our results." (PMID 37848651, 2024).
depression (continued). "This is different from our findings, with the group peaking at age 9 years and with decreasing CRP being associated with severe depression (along with psychotic disorder, PEs, and increased HOMA2 score) at age 24 years." (PMID 39167392, 2024). "Epidemiological evidence on the association between hs-CRP and depression in the general population has been inconsistent." (PMID 38596631, 2024). "CRP is a commonly used marker of chronic systemic inflammation, and elevated CRP levels have been linked to depression." (PMID 39203767, 2024). "Low physical activity, low depression scores, and unhealthy diet habits were associated with higher CRP and higher glucose and triglyceride levels, respectively." (PMID 39121088, 2024). "Large-scale epidemiologic studies and meta-analyses have demonstrated a strong association between IL-6 or CRP and mortality outcomes from a variety of causes (including diseases such as cancer, cardiovascular disease and depression)." (PMID 38952546, 2024). "An elevated CRP level was especially associated with a Montgomery–Åsberg Depression Rating Scale item 10 score ≥4 (P = .001)." (PMID 39283831, 2024). "Inflammatory biomarkers, such as high levels of C‐reactive protein (CRP), are often associated with fatigue and depression in cancer patients, as well as with unresolved and advanced disease in different types of cancer." (PMID 38819432, 2024). "Other meta-analyses have suggested associations between depression and elevated levels of inflammatory markers, such as C-reactive protein (CRP), IL-6 and, to a lesser extent, IL-1." (PMID 39358787, 2024). "C-reactive protein serves as a marker of inflammation and is linked to depression in the general population." (PMID 37848651, 2024). "Conversely, the association between CRP and depression persisted even after the adjustment for anxiety, suggesting disorder specificity." (PMID 38699297, 2024). "Depression has already been associated either with elevated serum levels of proinflammatory cytokines or acute phase proteins, such as C-reactive protein (CRP); however, in MDD cases, the immune-related gene expression was independent of serum CRP levels." (PMID 39457114, 2024). "In conclusion, a dose–response relationship was observed between higher serum magnesium levels and a lower depression risk, and this relationship was affected by CRP levels." (PMID 37049401, 2023). "The validity of our analysis was substantiated by replicating previous findings that showed associations between CRP and depression/fatigue severity." (PMID 36831896, 2023). "CRP has also been implicated in indirectly causing depression in individuals who also have an increase in cardiovascular disease risk." (PMID 37754956, 2023). "On the other hand, another recent meta-analysis, which included 22 studies and a total of 20,791 participants, revealed a positive association between depression and CRP and IL-6 levels." (PMID 34590201, 2023). "High CRP blood levels have been associated with neurological disease and depression, but little is known about the relationship between CSF and blood levels." (PMID 37445700, 2023). "In the development, progression and treatment of depression, an increasing number of researchers have focused on the association between CRP levels and depressive symptoms [including major depressive disorder (MDD) and treatment-resistant depression (TRD)]." (PMID 36860788, 2023). "Since then, the common inflammatory marker C-reactive protein (CRP) has been linked to both depression as a whole, and to specific symptoms such as fatigue, abnormal appetite, and cognitive dysfunction." (PMID 37614344, 2023). "Second, it has been shown that peripheral CRP is associated with a somatic symptom and energy-related phenotype of atypical depression, which in turn is associated with dysfunctional self-reported interoception." (PMID 36831896, 2023).
depression (continued). "Childhood traumatic events are recognized risk factors for depression and other mental illnesses and are associated with elevated levels of inflammatory markers such as CRP or IL-6." (PMID 37700748, 2023). "Higher levels of depression symptoms were associated with increased levels of pro-inflammatory biomarkers CRP and TNF-α in older nurses working in the United States." (PMID 37637801, 2023). "The increase of CRP and IL-6 in different age groups is related to the increased risk of depression, and the increased level of IL-6 in childhood is related to the occurrence of depression in adulthood." (PMID 36846218, 2023). "For example, MT-CYB, which was found to interact with CRP for self-reported depression, is the only mitochondrial DNA encoded subunit of respiratory complex III." (PMID 37344456, 2023). "For example, medical illnesses that cause increases in inflammatory factors such as interleukin-6 (IL-6), tumor necrosis factor-α (TNF-α), and C-reactive protein (CRP) increase the risk for depression." (PMID 37840796, 2023). "Psychosocial stress is associated with increased concentrations of C-reactive protein (CRP), IL-6, and IL-1β, inflammatory cytokines that have been consistently linked to depression." (PMID 36803835, 2023). "Previous work investigating the causal role of CRP, interleukin-6 (IL-6, major moderator of CRP), BMI and specific symptom dimensions of depression (sleep, appetite, suicidality) used LD score regression and a range of two-sample MR analyses." (PMID 37710313, 2023). "CRP is a commonly used marker of chronic systemic inflammation, and elevated CRP levels have been associated with depression." (PMID 37049401, 2023). "Individuals with CRP levels ≥ 5 mg/L (compared to those with CRP levels < 5 mg/L) were significantly associated with higher depression scores (β = 0.14; 95% CI = 0.04, 0.24; p = 0.005)." (PMID 37049401, 2023). "We also aimed to replicate previous findings on the associations of depression and fatigue severity with CRP." (PMID 36831896, 2023). "Nevertheless, for anxiety, associations were mainly limited to CRP and anxiety symptoms of irritability, a symptom also commonly present in depression." (PMID 37344456, 2023). "In our cohort of women with elevated depression and anxiety, specific pro-inflammatory cytokines, i.e., IL-6 and CRP, were positively associated with more elevated scores of depression and/or anxiety." (PMID 37107316, 2023). "Further studies are needed to verify the neurobiological pathways of the CRP-depression association in different subtypes." (PMID 36860788, 2023). "In the causal analyses for the reverse pathway (from depression outcomes to BMI and CRP), a significant proportion of SNPs were excluded in Steiger filtering as they appeared to be more strongly associated with CRP or BMI." (PMID 37710313, 2023). "In the GENDEP (genome-based therapeutic drugs for depression) study cohort, higher C-reactive protein levels were associated with better response with nortriptyline whereas lower levels were associated with better response in patients taking escitalopram." (PMID 37772416, 2023). "Among 133 retrospectively recruited patients with moderate–severe depression (both unipolar and bipolar), higher levels of baseline high-sensitivity CRP were associated with SA (p = 0.05), death (p = 0.018), and self-harm/self-injury thoughts (p = 0.011)." (PMID 38248245, 2023). "In particular, HIV-positive male patients with a high level of inflammation (CRP > 3 mg/L) showed a greater risk for depression." (PMID 38138916, 2023). "Elevated levels of CRP are associated with postoperative depression and predicts the length of hospital stay." (PMID 37928924, 2023). "In the same study, the genetic risk for lifetime depression was found to be positively correlated with serum CRP levels." (PMID 37111100, 2023).
depression (continued). "If the researchers have slimmed their options to IL-6 or CRP, they would want to decide which protein to target based on which protein is most strongly associated with depression." (PMID 37393056, 2023). "Hs-CRP can be used as a diagnostic marker for depression, especially for male patients with depression." (PMID 38020612, 2023). "This is consistent with previous research identifying a significant association between CRP levels and depression severity in patients with other types of cancer." (PMID 37444517, 2023). "Several meta-analyses have explored the association between CRP and depression in participants with either major or probable depression and found significant but small effect sizes." (PMID 36860788, 2023). "A large proportion of studies assessing the association between inflammation and depression use CRP as their marker of inflammation." (PMID 37928924, 2023). "In this study, we aimed to investigate the causal effects of CRP and BMI on depression-related phenotypes, including TRD, using various MR methods to overcome a series of methodological issues." (PMID 37710313, 2023). "Specifically, women with rheumatoid arthritis have elevated CRP and IL-6 levels, which contribute to the heightened risk of depression in female patients." (PMID 38062440, 2023). "According to the biochemical analysis, improvement of depression symptoms was associated with reduced level of CRP, increased production of BDNF, and incremented access brain to serotonin." (PMID 37537722, 2023). "We sought to substantiate the validity of our results by replicating previously presented evidence of a positive association between CRP levels and severity of depression and body-related experience of fatigue." (PMID 36831896, 2023). "For both patients and controls, levels of CRP were associated with worse symptomatology (i.e., depression and physical activity)." (PMID 37444517, 2023). "Higher CRP levels have been associated with an increased severity of depressive symptoms and risk of future depression." (PMID 37762207, 2023). "Adding to the confusion is the degree and duration of depression that was measured, although, in general, it was found that higher CRP was associated with greater severity of symptoms, rather than an increased risk of developing MDD." (PMID 38250276, 2023). "Depressive symptoms and major depression were associated with elevated levels of inflammatory biomarkers such as C-reactive protein (CRP), interleukin (IL)-1, IL-6, tumor necrosis factor-alpha (TNF-α) and monocyte chemoattractant protein-1 (MCP-1)." (PMID 36915045, 2023). "The prevalence and severity of depression were significantly associated with D-dimer, CRP, ferritin, PCT, and Interleukin-6 (p<0.05)." (PMID 37621784, 2023). "Depression is associated with inflammation by increasing C-reactive protein (CRP) and cytokines, such as interleukin-6 (IL-6) and tumor necrosis factor-α (TNF-α)." (PMID 37096248, 2023). "IL-6 wasindependently associated with depression; however, anxiety was associated with IL-33and CRP levels." (PMID 37712803, 2023). "The results revealed that, in contrast to depressive episodes, manic episodes were associated with higher levels of testosterone and CRP, and lower levels of ACTH." (PMID 37340368, 2023). "Second, studies have suggested that extreme levels of CRP are associated with treatment-resistant depression, and although there is an indication of large CRP concentrations in the UK Biobank sample, the depression phenotype is derived from a self-report." (PMID 36712567, 2023). "On the other hand, the mediation effect of CRP (mediator) accounted for 7.3% of the relationship between depression and all-cause mortality, and the strength of this association was not reduced by inflammation (direct effect)." (PMID 37587401, 2023).